FAP (fibroblast activation protein alpha)
Diseases named in the same sentence as FAP in open-access papers (continued):
Sharing a sentence is not in itself a finding about the gene and the disease.
diabetes (15 papers, 2016 to 2025). "High left ventricular FAP signal intensities as measured by positron-emission-tomography are associated with cardiovascular and metabolic risk factors such as hypertension, diabetes mellitus and obesity." (PMID 33667270, 2021). "In fact, FAP has recently been implicated in the regulation of metabolism due to the diabetes and obesity-resistant phenotype of the FAP knockout mouse." (PMID 26962859, 2016). "The multivariate modelling found an association between an increased uptake on FAP-specific PET and a hypothyroid metabolic state, overweight, diabetes mellitus as well as prior radiotherapy to the chest." (PMID 33606104, 2021). "Cancer patients in our study were older than controls and had comorbidities such as hypertension, diabetes or coronary artery disease, which could have influenced FAP levels." (PMID 40690098, 2025). "KEGG enrichment analysis further validated the significant association between high FAP expression and pathways like ECM-receptor interactions, focal adhesions, AGE-RAGE signaling in diabetes-related complications, HPV infection, and the PI3K-Akt signaling cascade." (PMID 38826849, 2024). "Similarly, the NFS and the FAP index differed significantly when diabetes was present, as both of these tools include the presence of diabetes as a key component of their score calculations." (PMID 38201904, 2023). "Patients with diabetes mellitus had a larger FAP volume (134 ± 53 cm3 vs. 93 ± 36 cm3, p = 0.012)." (PMID 39355018, 2023). "Diabetes mellitus, overweight, and aging were associated with increased FAPI uptake, suggesting metabolic changes and cardiac FAP activation might be related." (PMID 36072860, 2022). "As FAP protein is detected in human plasma, the pharmacological inhibition of FAP could be a therapeutic drug target for metabolic diseases, such as obesity and diabetes." (PMID 35159314, 2022). "Therefore, FAP inhibitors could prove even more useful in treating diabetes and metabolic disorders than may be expected from extending the lifetime of FGF-21 alone." (PMID 26962859, 2016). "The pathogenesis of heart failure with preserved ejection fraction (HFpEF) secondary to type 2 diabetes mellitus (T2DM) is complex, and the role of fibroblast activation protein (FAP) remains elusive." (PMID 40855978, 2025). "To discover novel and potent FAP inhibitors in our study, we screened > 800 compounds from a chemical library and identified BR103354 as a potential candidate for the treatment of diabetes and metabolic diseases." (PMID 33277568, 2020). "However, to the best of our knowledge, FAP concentrations are not effected by medication for diabetes or lipid disorders." (PMID 36568546, 2022). "The present results indicate that FGF-21 may be a biologically relevant substrate for FAP in humans, but not in mice and therefore, that FAP inhibitors may prove useful in the treatment of diabetes and metabolic disorders in humans by increasing the lifetime of FGF-21." (PMID 26962859, 2016).
liver cancer (15 papers, 2017 to 2026). An epithelial or non-epithelial malignant neoplasm that arises from the liver. "Specifically, we have identified FAP+ CAFs as a conserved cancer-associated fibroblast subtype that is significantly associated with patient survival, albeit with functional and spatial distribution heterogeneity within different forms of liver cancer." (PMID 39239526, 2024). "By further subtyping, we identified eight CAF subclusters, FAP+ CAFs, similar to the previously-reported matrix-associated CAFs, significantly enriched in all liver cancer types, were involved in ECM remodeling and angiogenesis, exhibiting functional heterogeneity across different tumor subtypes." (PMID 39239526, 2024). "In a mouse liver cancer model, fibroblast activation protein (FAP)–STAT3–CCL2 signaling in cancer-associated fibroblasts (CAFs) promoted tumor growth by enhancing MDSC mobilization and FAP-mediated tumor promotion, and MDSC mobilization in CAF was abolished in CCR2-deficient mice." (PMID 33297571, 2020). "Collectively, the augmented abundance of FAP+ CAFs emerges as a widespread phenomenon in tumors, despite potential functional diversity across various liver cancer subtypes." (PMID 39239526, 2024). "After deconvolution single cells into the bulk cohort (TCGA-LIHC/CHOL) as well as in tumor-AL paired scRNA-seq samples, a significant increase of FAP+ CAFs ratio in liver cancer samples was observed (Wilcoxon test, P < 0.01; paired t-test, P < 0.05)." (PMID 39239526, 2024). "The immunosuppressive role of FAP+ CAFs has been extremely studied in various types of cancers such as head and neck, pancreatic, breast, lung, and liver cancers." (PMID 37480115, 2023). "It was demonstrated in hepatic stellate cells that the conditioned media from liver cancer cells enhance the FAP expression in them in a STAT3-dependent manner." (PMID 36825204, 2023). "Then liver cancer was selected as example to experimentally validate the pro-tumor and immune regulative role of FAP in gastrointestinal cancers." (PMID 37325617, 2023). "We analyzed the composition of tissues from patients with liver cancer using immunofluorescence probes for FAP (a marker for fibrosis) and CD44 (a marker for cancer cells)." (PMID 32210281, 2020). "In this study, our FAP-CAR T cells could slow the tumor growth in multiple types of tumors in different mice models, including liver cancer PDX NCG mice models, 4T1 allograft BALB/c models and Panc02 allograft C57BL/6 models, warranting their wide application prospect in clinical practice." (PMID 39086477, 2024).
osteosarcoma (15 papers, 2009 to 2026). A usually aggressive malignant bone-forming mesenchymal neoplasm, predominantly affecting adolescents and young adults. "Although direct in vivo evidence in osteosarcoma is limited, the presence of FAP + CAFs is associated with poorer prognosis and stronger drug resistance." (PMID 40959080, 2025). "A clinical and in vivo study showed that high expression of FAP in osteosarcoma is significantly associated with the tumor size and clinical stage." (PMID 37316886, 2023). "Prior studies, including a meta-analysis which evaluated multiple cancer types including osteosarcoma, have found that high expression of FAP is associated with poor outcomes." (PMID 37333052, 2023). "In osteosarcoma, FAP has been shown to promote tumor progression by enhancing angiogenesis through activation of the AKT and ERK signaling pathways, and by facilitating cell proliferation, migration, and invasion." (PMID 40959080, 2025). "FAP is selectively overexpressed in CAFs and osteosarcoma cells, but shows minimal expression in normal fibroblasts." (PMID 40959080, 2025). "It is suggested that FAP regulated VEGF-A expression in osteosarcoma cells via the PI3K/AKT and ERK signaling pathways." (PMID 37316886, 2023). "Osteosarcoma (n = 96) and soft tissue sarcoma (n = 262) were among cancer types with the highest FAP expression." (PMID 37333052, 2023). "They revealed that the knockdown of FAP remarkably blocked the proliferation, migration, and invasion of osteosarcoma cells in vitro, suppressing mouse tumor growth and metastasis via the AKT signaling pathway." (PMID 37316886, 2023). "Chondroblastic and osteoblastic areas of osteosarcoma, both apparently showing different phenotypes, showed weak expression of FAP and DPP-IV." (PMID 19817894, 2009). "This unexpected observation may be in part due to the presence of a fibroblastic osteosarcoma tumor in our dataset and the broad expression of fibroblast markers (FAP, FBLN1) across all tumor cell clusters." (PMID 37609233, 2023). "Also, FAP implies pro-angiogenic properties in osteosarcoma by promoting vascular endothelial growth factor-A (VEGF-A) expression." (PMID 37316886, 2023). "In osteosarcoma cells, significant inhibition of cell proliferation, migration, and invasion was observed after a knockdown of the serine protease, representing the importance of FAP for the malignant behavior of these tumors after its upregulation." (PMID 34018010, 2021). "In osteosarcoma, FAP expression occurred only in tumor cells." (PMID 25775399, 2015). "Therefore, integrating FAP-targeted strategies with conventional chemotherapy may offer a synergistic approach to overcome resistance and improve clinical outcomes in osteosarcoma." (PMID 40959080, 2025). "Immunohistochemical examination identified multiple FAP+ and α-SMA+ fibroblasts in primary osteosarcoma lesions and lung metastatic nodules." (PMID 40959080, 2025). "Osteosarcoma tissue core from the cTMA was chosen to validate the presence of the CAF markers: α-SMA, integrin α11, FAP, collagen-1, FSP-1, CD140β, caveolin-1 and CD90." (PMID 38803925, 2024). "Currently, potential effective targets for CAR-T cell therapy in osteosarcoma include HER2, IGF1R, ROR1, EphA2, CSPG4, folate receptor with EC17, B7-H3, GD2, NKG2D, ALCAM/CD166, IL-11Rα, and FAP." (PMID 38187386, 2023). "PODN was regarded as a potential biomarker for the diagnosis and prognosis of osteosarcoma, ACTA2, COL6A1, FAP, OLFML2B and COL6A3, can be used as potential prognostic indicators for osteosarcoma." (PMID 34273970, 2021). "However, the cellular functional role that FAP plays in osteosarcoma (OS) remains unknown." (PMID 24520291, 2014). "Finally, it was determined that PODN has functional relevance in osteosarcoma and additional genes (ACTA2, COL6A1, FAP, OLFML2B and COL6A3) have prognostic significance for osteosarcoma." (PMID 34273970, 2021). "Furthermore, ACTA2, COL6A1, FAP, OLFML2B and COL6A3, can be used as prognosis biomarkers for osteosarcoma." (PMID 34273970, 2021).
osteosarcoma (continued). "Recently, some studies have reported FAP expression in some cancerous epithelial cells and osteosarcoma tumor cells; however, FAP expression was absent in normal adult tissues." (PMID 25775399, 2015). "Immunohistochemistry using pre-fixed frozen sections revealed that FAP was positive in low-grade myofibroblastic sarcoma, the fibroblastic component of osteosarcomas, and malignant fibrous histiocytomas, but negative in Ewing’s sarcomas and rhabdomyosarcomas." (PMID 19817894, 2009). "The present study has clearly shown that fibroblast-like spindle tumour cells strongly express FAP and DPP-IV in low-grade myofibroblastic sarcoma, fibroblastic areas of osteosarcoma, MFH, non-ossifying fibroma, desmoid tumour, and chondroblastoma." (PMID 19817894, 2009).
adenoma (14 papers, 2005 to 2024). A neoplasm arising from the epithelium. "Detection of PSG9 expression in adenomas, and at higher levels in FAP cases, indicates that germline APC mutations and defects in Wnt signalling modulate PSG9 expression." (PMID 15982419, 2005). "Inflammatory tissue was displayed in 38.9%, and the adenomas showed 27.5% FAP expression, whereas controls were completely devoid of FAP expression." (PMID 38397199, 2024). "Apc mutant mice develop large numbers of adenomas in their small intestine and fewer in the large intestine whereas; FAP patients develop low numbers of adenomas in their small intestine and large numbers of adenomas in their large intestine." (PMID 23530816, 2013). "The inducible cyclooxygenase-2 (COX-2) has been shown to be overexpressed in colorectal cancer and adenomas in humans and was demonstrated to be a controlling factor in the development of adenomas in a mouse FAP model." (PMID 17955050, 2007). "Early expression of PSG9 even before adenoma formation at the top of the crypts in FAP cases, suggests that transformation process starts in cells at the top of the crypts which then gradually move downward." (PMID 15982419, 2005). "A total of 27.5% of adenoma patients showed positive FAP expression." (PMID 38397199, 2024). "Moreover, there was a significantly higher level of FAP expression in inflammatory sites compared to adenomas (p = 0.02905; χ2 = 7.1)." (PMID 37614665, 2023). "Here, we have analyzed the immunohistochemical expression of FAP in 41 adenoma-carcinoma sequences." (PMID 32428869, 2020). "It has been reported that in all CRC samples examined, FAPα was expressed in cancer-associated fibroblasts, but not in normal colon, hyperplastic polyps, or adenoma samples." (PMID 31920487, 2019). "In 1990, one study detected FAP in all CRC samples, and one out of seven adenomas showed high FAP expression." (PMID 38397199, 2024). "Previously, it was reported that the activity and expression of two other serine peptidases, fibroblast activation protein alpha (FAP) and prolyl endopeptidase (PEP), was higher in adenomas and in early stages of CRC respectively." (PMID 25790122, 2015). "Other studies showed a 24% FAP expression in adenomas or no expression at all." (PMID 38397199, 2024). "However, FAP was only present in 1 of 24 (4%) adenomas and absent in non-neoplastic, non-inflammatory tissue (0/28)." (PMID 37614665, 2023). "Methods: 67 CRC, 24 adenomas, 18 tissue samples of inflammation sites and 28 non-neoplastic, non-inflammatory tissue samples of colonic mucosa were evaluated for immunohistochemical FAP expression of CAF in tissue microarrays." (PMID 37614665, 2023). "These authors demonstrated in vitro that medium conditioned by CRC cells, but not by adenoma cells, induces FAP expression in CAFs, suggesting that FAP may be a useful diagnostic marker for early CRC invasion." (PMID 32428869, 2020). "However, FAP was only present in 1/24 (4%) adenomas and absent in normal mucosa (0/28)." (PMID 37614665, 2023). "Consistent with previous reports, expression of FAP was detectable in the majority of CRC but nearly absent in precursor lesions (i.e., adenomas) and non-neoplastic, non-inflammatory tissue." (PMID 37614665, 2023). "The cytoplasmic levels of FAPα were significantly increased in invasive LARC cells after nCRT and tumor microenvironment immune cells in adenomas, while the adjacent non-neoplastic epithelial cells were negative." (PMID 34976180, 2022). "The staining of CXCL12, CXCR4, and FAPα was more intense in high-grade dysplastic epithelial cells and intramucosal invasive LARC cells than in the non-neoplastic epithelial cells of the 16 adenoma cases (p < 0.001 for each)." (PMID 34976180, 2022).
idiopathic pulmonary fibrosis (14 papers, 2014 to 2025). Idiopathic pulmonary fibrosis (IPF) is a nonneoplastic pulmonary disease that is characterized by the formation of scar tissue within the lungs in the absence of any known cause. "Before the emergence of fibroblast activation protein (FAP) tracer as a specific fibroblasttargeting agent, 18F-FDG-PET/CT had been investigated as a means to evaluate idiopathic pulmonary fibrosis (IPF)." (PMID 39439976, 2024).
esophageal cancer (13 papers, 2022 to 2025). A primary or metastatic malignant neoplasm involving the esophagus. "Using fibroblast activation protein (FAP) as a CAF marker, we previously revealed that FAP+ CAFs are linked to poor survival in patients with esophageal cancer." (PMID 41154405, 2025). "FAP has been shown to be overexpressed by cancer-associated fibroblasts (CAFs) in multiple epithelial cancers and other types of cancer and has been described for esophageal cancer before." (PMID 38575990, 2024). "In the present study, we found that EGFR is not only involved in the survival of esophageal cancer patients but is also associated with poor survival in association with FAP, which is a novel finding evaluating the association between EGFR signaling and the stroma in clinical specimens." (PMID 36418422, 2022). "In clinical esophageal cancer samples, FAP expression strongly correlated with increased collagen I, hyaluronic acid, and microvascular collapse." (PMID 41424387, 2025). "FAP immunohistochemistry (IHC) scoring demonstrated strong FAP expression in 50–100% of esophageal cancer cases, which was declared to be one of the highest among the fourteen investigated cancer types." (PMID 37608378, 2023). "To explore the expression of EGFR, HER2, and FAP in esophageal cancer, we conducted IHC using surgically resected tissues." (PMID 36418422, 2022). "We demonstrated the relationship between EGFR/FAP expression and prognosis of patients with esophageal cancer and the stronger therapeutic effect of dual-targeted NIR-PIT than single-targeted NIR-PIT in experimental models." (PMID 36418422, 2022). "Notably, outcomes in head and neck, NSCLC, and esophageal carcinomas appeared to be unaffected by FAP expression." (PMID 38558814, 2024). "In our analysis, we describe the impact of dual-tracer imaging with Gallium-68-radiolabeled inhibitors of FAP (FAPI-46-PET/CT) and fluorodeoxy-D-glucose (FDG-PET/CT) on the radiotherapeutic management of primary esophageal cancer (EC)." (PMID 38575990, 2024). "Here, we examined the clinicopathological relationship between the ErbB tyrosine kinase receptor family and CAFs in clinical samples and demonstrated that both high FAP and EGFR expression strongly contributed to esophageal cancer prognosis." (PMID 36418422, 2022). "A total of 132 cases of esophageal cancer were analyzed for epidermal growth factor receptor (EGFR), human epidermal growth factor 2 (HER2), and fibroblast activation protein (FAP) expression using immunohistochemistry." (PMID 36418422, 2022). "According to the results of the present study, 68Ga-FAPI-RGD may be more suitable for imaging tumors with both FAP and integrin αvβ3 expression, particularly for NSCLC and esophageal cancer." (PMID 37142301, 2023). "Thus, dual-targeted NIR-PIT is a reasonable treatment for esophageal cancer patients with poor prognosis expressing both EGFR and FAP, as it can simultaneously attack both cancer cells and stroma and break the relationship." (PMID 36418422, 2022). "Thus, high expression of both FAP and EGFR strongly contributed to the prognosis of esophageal cancer." (PMID 36418422, 2022).
metastatic colorectal cancer (13 papers, 2014 to 2025). "Unsurprisingly, another trial with FAP inhibitor talabostat in metastatic colorectal cancer patients also proved ineffective." (PMID 40741380, 2025). "Single-agent FAP inhibitor Val-boroPro (Talabostat) had minimal activity in patients with previously treated metastatic colorectal cancer in a phase II trial, despite significant, but incomplete inhibition of FAP enzymatic activity in the peripheral blood." (PMID 37046676, 2023). "The clinical impact of FAP-α was also tested using Val-boroPro (Talabostat), the first clinical inhibitor of FAP-α enzymatic activity, in a phase II study of patients with metastatic colorectal cancer." (PMID 24885257, 2014). "However, depletion of FAP+ stromal cells failed in metastatic colorectal cancer while depletion of αSMA+ fibroblasts resulted in an unexpected more invasive cancer with increase hypoxia and EMT." (PMID 38313431, 2023). "In a phase II trial of patients with metastatic colorectal cancer, sibrotuzumab, an antibody targeting FAP did not meet the criteria for a minimal response." (PMID 37046676, 2023). "Nevertheless, lethal bone toxicity and cachexia were observed in FAP+ stromal-cells-depleted murine models, and in clinical trials, anti-FAP inhibitors showed no therapeutic benefit in patients with metastatic colorectal cancer." (PMID 36671447, 2022). "However, given that FAP inhibitors had underwhelming results in clinical trials with metastatic colorectal cancer patients, direct targeting of FAP+ cells were not pursued in PDAC." (PMID 34948209, 2021). "In a phase II trial with metastatic colorectal cancer patients, the enzymatic activity of FAP could not be inhibited, and no efficacy was not demonstrated, although a humanized anti-FAP antibody (mAb F19; sibrotuzumab) was well tolerated." (PMID 33462372, 2021).